WNT5A (Wnt family member 5A)
Diseases named in the same sentence as WNT5A in open-access papers (continued):
Sharing a sentence is not in itself a finding about the gene and the disease.
melanoma (continued). "Hypoxia induced switching of the expression of ROR1 and ROR2 through non-canonical WNT5A signaling, resulting in an invasive phenotype of melanoma with reduced sensitivity to BRAF inhibitors." (PMID 25763355, 2015). "In addition to TGFβ and WNT5A signaling, EGF, FGF, MET, and IGF signaling have established roles in conferring migratory and invasive functions in melanoma." (PMID 25763355, 2015). "Investigators further demonstrated that BRAFi-resistant melanoma cell lines overexpressed WNT5A protein and that WNT5A expression was not affected by the removal of BRAFi." (PMID 26393652, 2015). "Whereas in these MITF‐negative cells, factors such as WNT5A and TGFβ appear to dominate the regulation of melanoma cell fate, in the MITF‐positive cells, MITF is the central regulator of melanoma cell survival, proliferation and differentiation." (PMID 25818589, 2015). "In the cell lines we examined the cellular levels of Wnt5a do not correlate with secreted Wnt5a levels in melanoma cell lines." (PMID 26029828, 2015). "WNT5a, in particular, by binding to the Frizzled4- LRP6 complex, activates ARF6 (guanosine triphosphatase adenosine diphosphate ribosylation factor 6), leading to displacement of β-catenin from N-cadherin in melanoma." (PMID 24743024, 2014). "The later stages of melanoma including the spread to distant sites and the formation of metastasis have been shown to be promoted by an increased non-canonical WNT5A signaling." (PMID 24766647, 2014). "WNT5A is a non-canonical Wnt protein that previously has been shown to play a role in the progression of malignant melanoma." (PMID 24766647, 2014). "In the present study we present novel data showing that the non-canonical Wnt protein WNT5A, has an effect on release of exosomes containing immunomodulatory and pro-angiogenic factors in malignant melanoma cells." (PMID 24766647, 2014). "Immunohistochemical analyses revealed that Wnt5a staining was negative in the majority of benign tumors and was heterogeneously distributed among primary melanomas, while the majority of metastatic tumors were stained strongly positive for Wnt5a." (PMID 24944588, 2014). "According to the literature, Wnt5a dependent E-cadherin down-regulation, however, is independent of the canonical Wnt pathway in melanoma type skin cancer and favours the PKC dependent up-regulation of a transcriptional repressor, Snail." (PMID 23505429, 2013). "More recently, it was shown that direct antagonism of Wnt5A signaling by using a targeted, synthetic peptide inhibitor of the Wnt5A pathway could inhibit Wnt5A-dependent and PKC-dependent increases in melanoma cell migration and invasion." (PMID 24281103, 2010). "The role of Wnt5A mediated signaling in cell motility and other intermediary proteins (e.g. Ena/VASP, Arp2/3) in filopodia formation has been investigated in human and mouse melanoma cells." (PMID 20454608, 2010). "Both Wnt1 and Wnt3a have been shown to activate RhoA, whereas the non-canonical Wnt5a promotes melanoma migration via RhoB." (PMID 19473496, 2009). "Many of the non-canonical Wnt signalling pathways target the cytoskeleton, as in melanoma where non-canonical signalling by WNT5a is found to correlate with metastatic potential and invasiveness." (PMID 19874621, 2009). "In the already amoeboid HTB63 cells, on the other hand, there was no phenotypic switch, suggesting that impaired WNT5A signaling specifically induces rounded amoeboid migration in melanoma cells that exhibit a predominantly elongated mesenchymal mode of migration." (PMID 33969605, 2021). "Thus, RND3‐RhoA signaling presents a possible compensatory mechanism in wild‐type BRAF and BRAFV600‐mutant melanoma cells treated with a BRAF inhibitor, suggesting that it could be a potential drug target in combination with WNT5A interference." (PMID 33969605, 2021).
melanoma (continued). "It is possible that this phenomenon could be related to an ability of WNT5A to regulate melanoma cell plasticity, although this hypothesis has not been completely studied." (PMID 33969605, 2021). "Elevated expression of WNT5A associates with negative overall survival in melanoma; we have observed an inverse correlation for RNF43, which was a positive prognostic factor in melanoma and got silenced as melanoma progressed." (PMID 34702444, 2021). "This mesenchymal‐to‐amoeboid transition is in good accordance with our observation that WNT5A knockdown does not completely inhibit melanoma cell invasion and suggests the presence of a compensatory mechanism through which melanoma cells are able to invade a 3D collagen matrix." (PMID 33969605, 2021). "In addition to activation of the non-canonical signaling pathways, WNT5a was reported to activate the canonical CTNNB1 pathway in the presence of FZD4 receptors in melanoma cells." (PMID 32546756, 2020). "WNT5A modulates melanoma cell behavior via multiple cell surface receptors/co-receptors, including ROR2 and Frizzleds, and downstream molecular targets, such as APT1, IL-6, and PKC-STAT3, which in turn affect various melanoma cell functions, including migration and invasion." (PMID 32033033, 2020). "However, a possible functional role of the MARCKS protein in WNT5A-induced melanoma cell migration and invasion has not yet been studied." (PMID 32033033, 2020). "Therefore, it has been suggested that lack of nuclear β-catenin and high level of cytoplasmic WNT5A can be indicatives of unfavorable prognosis for melanoma patients." (PMID 32659938, 2020). "In melanoma samples, a negative correlation of Wnt5A and Klotho expression has been observed." (PMID 32585905, 2020). "Based on a previous finding that the MARCKS protein has been implicated in the formation of such structures and our present results, we speculated that WNT5A signaling could promote melanoma cell migration and invasion via translocation of phosphorylated MARCKS to the leading edge of melanoma cells." (PMID 32033033, 2020). "However, a possible direct contribution of MARCKS in WNT5A-mediated melanoma cell invasion has not been investigated." (PMID 32033033, 2020). "Interestingly, we demonstrated that inhibition of PKC and ROCK signaling blocked WNT5A-mediated MARCKS phosphorylation and melanoma cell invasion, which indicated that both PKC and RhoA-ROCK, as intermediate signaling pathways, are crucial during WNT5A-regulated MARCKS function." (PMID 32033033, 2020). "However, in contrast to this latter finding, we found that the IL‐6/WNT5A positive feedback loop is absent in BRAFi‐R melanoma cells." (PMID 30582770, 2019). "Moreover, WNT5A induces depalmitoylation of melanoma cell adhesion molecule (MCAM) and, subsequently, polarizes localization of MCAM and CD44 (another cell adhesion molecule) to promote directional movement and invasion of melanoma cells." (PMID 30166456, 2018). "Thus, different combinations of therapies should be effective in treating different phases of melanoma, such as the combination of targeted therapies with inhibitors of MITF expression during the initial treatment phase, but with inhibitors of WNT5A/AXL/NF-κB signaling during relapse." (PMID 29881716, 2018). "Finally, overexpression of STIM1 and Orai1 failed to restore SOCE in any of the Wnt5a-expressing invasive melanoma cell lines examined." (PMID 27417567, 2016). "Interestingly, WNT-5A induces redistribution of CD146 and accumulation of a unique membrane complex composed of actin, myosin IIB, and FZD3 (termed W-RAMP) asymmetrically at the cell periphery in a DVL- and PKC-dependent manner in melanoma cells." (PMID 26514730, 2016). "A role for Wnt5a in melanoma progression through both canonical and non-canonical signal transduction has been demonstrated, which may be modulated by ARF signaling." (PMID 27589803, 2016).
melanoma (continued). "However, we found only a poor correlation (Pearson correlation = 0.194) between WNT5A and IL-6 mRNA expression (data not shown) in the invasive melanoma cell lines." (PMID 27191257, 2016). "Consequently, knockdown of WNT5A signaling via siRNA treatment in BRAFi-resistant A375 melanoma cells led to a significant decrease in phospho-AKT (active form) in a PI3K-dependent manner, suggesting that WNT5A regulates PI3K-AKT in melanoma." (PMID 26393652, 2015). "We propose that interfering with WNT5A signaling will affects PI3K-AKT and the β-catenin-MITF-EGFR axis, which would make Box-5 therapy useful for not only BRAFi-resistant melanomas but also melanomas that do not carry BRAF mutations." (PMID 26393652, 2015). "In addition, Wnt-5a, in the presence of a CXCL12 chemokine gradient, was able to polarise the cellular cytoskeleton of WM239a melanoma cells through a process dependent on dishevelled (DSH), RhoB and Rab4 to promote cellular migration towards the source of the chemokine." (PMID 19603030, 2009). "As these findings and our present data demonstrate a WNT5A-IL-6 positive feedback loop in WM852 melanoma cells, we investigated whether targeting both these factors simultaneously could be a more efficient way to reduce or inhibit melanoma cell migration and invasion." (PMID 27191257, 2016). "WNT5a is involved in non-canonical WNT signaling, and can drive the switch to a metastatic phenotype and cytoskeleton remodeling in melanoma." (PMID 36230844, 2022). "In contrast to our previous findings showing a regulatory role of WNT5A in MARCKS expression and activation in BRAFi-sensitive melanoma cells, our present investigation revealed a lack of such a relationship in BRAFi-R melanoma cells." (PMID 36551563, 2022). "Surprisingly, neither WNT5A nor IL-6 contributed to the increases in MARCKS expression and activity in BRAFi-R melanoma cells, unlike in BRAFi-sensitive melanoma cells." (PMID 36551563, 2022). "This suggests that activation of noncanonical WNT5A-induced signaling and ROR1 and ROR2 changes is indeed a part of the melanoma adaptation mechanism to vemurafenib." (PMID 34702444, 2021). "The components of the Wnt5a-ROR signaling pathway have been shown to overexpress in several hematological and non-hematological malignancies, including breast, colon, melanoma, lung, and pancreatic cancer." (PMID 34319035, 2021). "And lastly, secreted WNT5A (as opposed to WNT3A) has been shown to negatively regulate WNT/β-catenin signaling in several cancer types, including in a subgroup of melanoma patients exhibiting acquired resistance to BRAF-inhibition." (PMID 32238882, 2020). "The results revealed that all four melanoma cell lines (WM852, HTB63, A375 and A2058) used in our study expressed significant levels of MARCKS irrespective of their WNT5A levels." (PMID 32033033, 2020). "When Wnt5a interacted with Frizzled3 (Fz3), a noncanonical Wnt receptor, in WM239A melanoma cells, the Wnt signal was initiated and relayed by Disheveled-2 (DVL2), which recruited CD146 to bind." (PMID 25685061, 2015). "It is not clear what upregulates AXL or WNT5A expression, but BRAF inhibition in a panel of BRAFmut/AXL+ melanoma cells does not reduce AXL expression." (PMID 25818589, 2015). "On the contrary, our study has not demonstrated the involvement of Wnt5a/PKC pathway in ES metastasis, though it is well established that this pathway plays a crucial role in melanoma invasion." (PMID 23075330, 2012). "WNT5A silencing resulted in significant decreases in the protein levels of both total MARCKS and its active phosphorylated (Ser-159/163) form in BRAFi-sensitive melanoma cells, but no reductions were observed in either of the two BRAFi-R2 melanoma cell lines." (PMID 36551563, 2022).
melanoma (continued). "Recent studies have emphasized the importance of WNT5A in regulating the EMT, thus stimulating cell migration, invasion, and aggressiveness in gastric, pancreatic, ovarian, and malignant melanoma; however, the role of WNT5A in ESCC has not been previously investigated." (PMID 35595735, 2022). "While MITF expression does not seem to be relevant in this melanoma cell population, both WNT5A and AXL expressions correlate with clinical response and therapy resistance, suggesting that assessing the AXL/WNT5A expression status could be used as prognostic and/or predictive marker." (PMID 25818589, 2015). "Interestingly, Wnt5a does not exlusively mediate its effects on melanoma cells via a non-canonical, protein kinase C (PKC) dependent Wnt signaling pathway, but also stimulates β-catenin transcriptional activity during Wnt5a-mediated melanoma invasion and metastasis." (PMID 29454361, 2018).
breast carcinoma (180 papers, 1998 to 2026). "This correlation suggests the potential clinical importance of Wnt5a as a diagnostic tool for breast cancer." (PMID 38273859, 2023). "ROR1 and ROR2 are Type 1 tyrosine kinase-like orphan receptors for Wnt5a that are associated with breast cancer progression." (PMID 37029329, 2023). "In breast cancer, WNT5A is considered a tumor suppressor since loss of WNT5A is associated with poor prognosis." (PMID 36476423, 2022). "Dual luciferase reporter assays and chromatin immunoprecipitation were performed to test the role of FOSL2 in regulating Wnt5a expression, and Wnt5a in the serum of the patients was measured to assess its clinical diagnostic value for breast cancer patients." (PMID 33754039, 2021). "This study aimed to investigate the mechanisms underlying the poor prognosis in Wnt5a-positive breast cancer patients." (PMID 34047951, 2021). "In contrast to WNT5B, many publications show WNT5A as a tumor suppressor in breast cancer, correlating its loss with a worse prognosis." (PMID 34017835, 2021). "In line with this, it has been shown that loss of Wnt5a expression, as a tumor suppressor, significantly correlates with stimulation of progression and metastasis of breast cancer cells and reduction of disease-free survival and overall survival." (PMID 34603445, 2021). "ALCAM expression levels (mRNA and protein) appear to be induced by the presence of Wnt5a in breast cancer cells, an expression event that is linked to the migration of breast cancer cells." (PMID 34680335, 2021). "As shown for breast cancer cells, the secretion of both tumor MV as well as Exo induced the expression of Wnt5a in tumor-associated macrophages." (PMID 32731639, 2020). "The loss of Wnt5a was found to be an indicator of poor prognosis in a study of whole breast cancers, including different subtypes." (PMID 29765514, 2018). "Loss of WNT5A has been associated with poor prognosis in a number of different cancer types such as breast cancer, colon cancer, neuroblastoma, and leukemia, thus suggesting a tumor-suppressive function of WNT5A in these tumor subtypes." (PMID 30171384, 2018). "The accumulated in vitro results reveal that treatment of WNT5A-negative breast cancer cells with recombinant WNT5A caused different tumor-suppressive responses and in particular it impaired migration and invasion." (PMID 30171384, 2018). "In other tumors, such as colorectal cancer, esophageal squamous cell carcinoma, thyroid carcinoma, breast cancer, and white blood cell disease, Wnt5a shows low expression or loss of expression and plays the role of a tumor suppressor gene." (PMID 30079293, 2018). "Overall, studies of WNT5A protein expression in breast cancer tissue reveal that it functions as a tumor suppressor in this type of cancer, where its loss correlates with breast cancer progression and metastasis." (PMID 30171384, 2018). "Pukrop and co-workers have suggested that macrophage-derived WNT5A is the cause of macrophage-induced invasiveness of breast cancer cells." (PMID 30171384, 2018). "Another independent investigation revealed loss of or reduced WNT5A protein expression in the tumor tissue from 56% of the included breast cancer patients." (PMID 30171384, 2018). "Wnt5a enrichment in breast cancer cell (SKBR-3)–derived exosomes is associated with macrophage-induced invasion of breast cancer cells." (PMID 29484119, 2018). "In breast cancer, loss of WNT5A expression has been associated with early relapse and unfavorable prognosis." (PMID 29069720, 2017). "Due to the inhibition of breast cancer cell migration, even in the presence of extracellular lactate, the WNT5A-mimic peptide, Foxy5, is implicated as a potential therapeutic agent in the treatment of extremely glycolytic and aggressive breast cancers." (PMID 29069720, 2017). "In this present study, we sought to extend our earlier observations of TLR3 and Wnt5a association and their role in tumor viability/growth and migration in human breast cancer." (PMID 29371911, 2017).